FGF23 (fibroblast growth factor 23)
Diseases named in the same sentence as FGF23 in open-access papers (continued):
Sharing a sentence is not in itself a finding about the gene and the disease.
osteoporosis (continued). "Further investigations showed persistent hypophosphataemia with high renal phosphate wasting (phosphate excretion 87 mmol/24 h, normal: 12–42 mmol/24 h), high FGF23—423 RU/mL (0–100 RU/mL), and signs of severe osteoporosis in densitometry." (PMID 38542041, 2024). "De hecho, el FGF23 y la esclerostina ya son dianas terapéuticas tras el desarrollo de anticuerpos contra estas proteínas en el tratamiento del XLH y la osteoporosis respectivamente." (PMID 38634083, 2024). "Evidence of an FGF23-mediated phosphate wasting disorder and osteoporosis also is observed in Enpp1asj mice, which also exhibit increased plasma intact FGF23, low plasma phosphate, and osteoporosis at 10 and 23 weeks of age on a regular chow diet." (PMID 37871131, 2024). "A nivel paracrino, también parecen existir conexiones entre el FGF23 y algunas alteraciones del remodelado óseo, como las mutaciones del Wnt1 que ocasionan osteoporosis precoz y fractura prevalente." (PMID 38634083, 2024). "Most recently, the fibroblast growth factor-23 (FGF23)/Klotho axis has been demonstrated to play the underlying connection between VC and osteoporosis." (PMID 37091976, 2023). "FGF23, as an osteocyte-originated hormone and key regulator of phosphorus and vitamin D, plays an important role in the pathogenesis of osteoporosis and TBS decline." (PMID 37507659, 2023). "Over the last ten years, the association between fibroblast growth factor 23 (FGF23) and osteoporosis has been studied in both pre-clinical and clinical investigations." (PMID 35269640, 2022). "The potential use of FGF23 as a biomarker for osteoporosis, CKD-MBD and fragility fracture prediction is also discussed." (PMID 35269640, 2022). "TNFα induces osteocyte apoptosis through NF-kB activation contributing to osteoporosis in postmenopausal women, and it induces osteocyte apoptosis and FGF23 increase in glucocorticoid-induced osteoporosis." (PMID 35216216, 2022). "In the present study, we evaluated the relationship between FGF21 and FGF23 and osteoporosis in a population-based retrospective HD cohort." (PMID 34011291, 2021). "Specifically, these patients exhibit mildly elevated FGF23, decreased serum phosphorous, elevated urinary Pi clearance, and radiographic evidence of osteoporosis." (PMID 34539972, 2021). "Ultimately, we explored the predictive values of serum FGF21 and FGF23 on osteoporosis in our HD cohort." (PMID 34011291, 2021). "Compared with control mice, they showed significantly elevated levels of plasma phosphate, FGF23 and 1,25-dihydroxyvitamin D, ectopic calcification in the kidney and aging-related phenotypes like growth retardation, osteoporosis and shortened lifespan." (PMID 29720668, 2018). "FGF23 signals via a complex of anFGF receptor (FGFR1(IIIc)) and Klotho; mice with a loss-of-functionmutation in Klotho develop osteoporosis amongst otherabnormalities, and modest evidence of association of Klotho withBMD has been reported in several studies." (PMID 21533022, 2011). "Additionally, as a hormone secreted by osteoclasts and osteoblasts, fibroblast growth factors (FGF-23) can provide new treatment options for osteoporosis." (PMID 39200293, 2024). "Therefore, there is insufficient evidence to determine the role of FGF23 in the pathogenesis of osteoporosis to date." (PMID 38732094, 2024). "Osteoporosis patients typically have higher levels of FGF23." (PMID 37198647, 2023). "A cross-sectional study of 28 patients with PMO, 32 with postmenopausal osteopenia and 30 healthy control subjects (postmenopausal non-osteoporosis) found that significantly higher levels of FGF-23 in the PMO group compared to the postmenopausal osteopenia and control groups." (PMID 35574015, 2022). "Preclinical reports have demonstrated the possible effect of FGF23 on osteoporosis pathogenesis." (PMID 35269640, 2022). "In addition, utilizing the FGF23 level for osteoporosis prediction in hemodialysis patients resulted in poor discrimination." (PMID 35269640, 2022).
osteoporosis (continued). "As a bone-derived hormone, FGF23 can act on kidneys and parathyroid glands to regulate bone metabolism activity, which may offer new options for the treatment of osteoporosis and other bone diseases." (PMID 35574015, 2022). "Our results suggest that lipocalin-2 is not a specific biomarker for WNT1 and PLS3 osteoporosis, but the correlation between lipocalin-2 and FGF23 indicates an association between these markers in bone biology." (PMID 36157448, 2022). "ROC curves were constructed to compare the prognostic value of FGF21 and FGF23 for osteoporosis." (PMID 34011291, 2021). "We hypothesized that AR could modulate the VD/FGF23/Klotho signaling pathway to alleviate osteoporosis." (PMID 34304712, 2021). "We assessed the correlation of CT attenuation values with serum FGF21 and FGF23 levels and tested whether they were independent factors for osteoporosis." (PMID 34011291, 2021). "The relationship between FGF23 and bone mineralization may be similar in other bone diseases like osteoporosis." (PMID 32155909, 2020). "Serum FGF-23 level is a significant determinant of increased bone turnover at early periods in postmenopausal osteoporosis patients so compounds which target FGF23 might be of value in the treatment of osteoporosis." (PMID 31194807, 2019). "The serum FGF-23 level was highest in the osteoporosis group." (PMID 29665846, 2018). "Furthermore, another cross-sectional study in osteoporosis patients, in which the majority are women, demonstrated a weak independent association between high FGF23 and deceased trabecular bone microarchitecture but not cortical bone." (PMID 35269640, 2022). "Serum FGF23 is reported to be independently correlated with vascular calcification but not mineral density in CKD patients while vascular calcification and osteoporosis appear to be independent processes in elderly women." (PMID 37112600, 2023). "The major limitation of this study was the lack of measurement of parameters involved in the pathogenesis of osteoporosis, such as PTH, FGF23, OPG, RANK, and RANKL." (PMID 37507659, 2023). "We investigated the therapeutic effect of AR on osteoporosis using SAMP6 mice as experimental material and examined the gene and protein expression content of VD/FGF23/Klotho signaling pathway." (PMID 34304712, 2021). "Previous studies have reported limited improvements in Ca and P metabolism and in serum fibroblast growth factor 23 after kidney transplantation, but no studies have documented recovery from osteoporosis or improvements in BMD." (PMID 40353207, 2025). "In fact, FGF23 and sclerostin are currently being used as therapeutic targets after the development of antibodies against these proteins for the treatment of XLH and osteoporosis, respectively." (PMID 38634076, 2024). "Another study in men with osteoporosis also showed that femoral neck BMD was not significantly changed in different FGF23 quartiles." (PMID 35269640, 2022). "This review comprehensively summarizes and discusses preclinical and clinical reports on the roles of FGF23 on osteoporosis, with an emphasis on the local action, as opposed to the systemic action, of FGF23 on the bone." (PMID 35269640, 2022). "In conclusion, FGF-21 and FGF-23, as members of the FGF subfamily, are involved in MetS and bone metabolic activities and may subsequently provide new options for the treatment of osteoporosis and MetS." (PMID 35574015, 2022). "Serum FGF21 levels were significantly higher in the osteoporosis group (P < 0.001), while serum FGF23 levels were not significantly different between these two groups." (PMID 34011291, 2021). "Those parameters that were different between the osteoporosis and non-osteoporosis groups and well-known risk factors, such as dialysis duration, SBP, Hb, Alb, TG, Ca, Pi, iPTH and FGF23, were all included in multivariate linear regression analyses." (PMID 34011291, 2021).
osteoporosis (continued). "First, we compared the serum FGF21 and FGF23 levels in patients on HD with or without osteoporosis on the basis of CT attenuation values." (PMID 34011291, 2021). "In contrast to FGF21, we observed that FGF23 had no value in predicting osteoporosis, although FGF23 had been proven to play a significant role in bone metabolism." (PMID 34011291, 2021). "The proteins secreted by osteocytes, such as fibroblast growth factor-23 (FGF23), sclerostin (SOST), and dickkopf-1 (DKK1), could be candidates for osteoporosis screening and fracture prediction." (PMID 32155909, 2020). "In view of the specific role of osteocyte-related proteins such as DKK-1, SOST, and FGF23 in regulating bone health, it is tempting to speculate that their circulating levels could predict BMD, osteoporosis, and fracture." (PMID 32155909, 2020). "For example, in the path of Calcitriol-Osteoporosis-FGF23, calcitriol is known to be useful in the treatment of osteoporosis, but it is not known why." (PMID 31194807, 2019). "Chronic inflammation status, parathyroid hormone abnormalities, and elevating circulating levels of fibroblast growth factor 23 (FGF23) could affect normal osteoblast function in chronic kidney disease stage 5D (CKD stage 5D) patients, resulting in osteoporosis." (PMID 35454336, 2022). "Indeed, in diabetic patients with osteoporosis, serum FGF23 level was decreased compared with those without osteoporosis." (PMID 27504998, 2016). "Despite numerous investigations on the influence of fibroblast growth factor 23 (FGF23), α‐Klotho and FGF receptor‐1 (FGFR1) on osteoporosis (OP), there is no clear consensus." (PMID 39054573, 2024). "Even though FGF23 levels had an independent negative relationship with BMD in postmenopausal women, it was not an effective discriminator between osteopenia/osteoporosis and normal bone mass." (PMID 35269640, 2022).
mesenchymal tumors (53 papers, 2011 to 2026). "Phosphaturic mesenchymal tumor (PMT) is a rare benign mesenchymal tumor characterized by excessive secretion of fibroblast growth factor 23 (FGF23), leading to phosphate loss and systemic osteomalacia." (PMID 39866529, 2025). "Oncogenic osteomalacia is most commonly caused by a phosphaturic mesenchymal tumour secreting FGF23 (hereinafter referred to as FGF23+ PMT), which usually shows benign features." (PMID 40981193, 2025). "Tumor-induced osteomalacia (TIO) is a rare acquired paraneoplastic syndrome caused by a mesenchymal tumor secreting a phosphaturic hormone called FGF23." (PMID 39888445, 2025). "Tumor‐induced osteomalacia (TIO) is a rare paraneoplastic syndrome caused by mesenchymal tumors that secrete fibroblast growth factor 23 (FGF23)." (PMID 36511653, 2023). "Tumor-induced osteomalacia (TIO), also known as oncogenic osteomalacia, is a rare paraneoplastic syndrome mainly caused by small phosphaturic mesenchymal tumors (PMTs) that secrete fibroblast growth factor-23 (FGF-23)." (PMID 37554164, 2023). "Tumor‐induced osteomalacia (TIO) is a rare paraneoplastic syndrome caused by ectopic production of fibroblast growth factor 23 (FGF23) by phosphaturic mesenchymal tumors (PMTs)." (PMID 35991529, 2022). "Tumor‐induced osteomalacia (TIO) is caused by phosphaturic mesenchymal tumors producing fibroblast growth factor 23 (FGF23) and is characterized by impaired phosphate metabolism, skeletal health, and quality of life." (PMID 33338281, 2021). "Tumour-induced osteomalacia (TIO) is caused mainly by mesenchymal tumours and is associated with low phosphate levels due to paraneoplastic FGF23 overproduction." (PMID 31993875, 2020). "We report the case of a 66-year-old woman with TIO caused by a FGF-23 secreting mesenchymal tumor localized in the axial skeleton, more specifically in the fourth lumbar vertebra." (PMID 23346426, 2012). "We report the case of a 66-year-old woman with tumor-induced osteomalacia (TIO) caused by fibroblast growth factor 23 (FGF-23) secreting mesenchymal tumor localized in a lumbar vertebra and review other cases localized to the axial skeleton." (PMID 23346426, 2012). "TIO is a rare paraneoplastic syndrome caused by a mesenchymal tumour that secretes FGF23." (PMID 40890774, 2025). "The cause is a mesenchymal tumor secreting fibroblast growth factor 23 (FGF23)." (PMID 36337019, 2022). "TIO is a rare syndrome characterized by bone pain, fractures and muscle fatigue/weakness caused by small mesenchymal tumors that may be found in bone or soft tissue that secrete FGF23." (PMID 32547492, 2020). "A computed tomography (CT) guided needle biopsy showed a low grade spindle cell neoplasm with positive FGF-23 mRNA expression by reverse transcriptase polymerase chain reaction (RT-PCR), confirming the diagnosis of a phosphaturic mesenchymal tumor mixed connective tissue variant (PMTMCT)." (PMID 23346426, 2012). "Surgical excision was performed, and histopathology confirmed a phosphaturic mesenchymal tumor with positive FGF23 in situ hybridization." (PMID 41737823, 2026). "Oncogenic osteomalacia (OOM), also known as tumor-induced osteomalacia (TIO), is a rare paraneoplastic syndrome caused by excessive production of fibroblast growth factor 23 (FGF23) by mesenchymal tumors." (PMID 41438661, 2026). "FGF23 is the central pathogenic factor in tumor-induced osteomalacia (TIO), and elevated levels provide strong support for the diagnosis of phosphaturic mesenchymal tumors (PMTs)." (PMID 39866529, 2025). "Tumor-induced osteomalacia (TIO) is a rare paraneoplastic syndrome of abnormal phosphorus metabolism caused by increased secretion of fibroblast growth factor 23 (FGF23) by small mesenchymal tumors." (PMID 40922882, 2025). "Clinically, phosphaturic mesenchymal tumors associated with FN1-FGFR1 fusion proteins cause increased FGFR1 signaling, resulting in ectopic FGF23 synthesis." (PMID 41473314, 2025).
mesenchymal tumors (continued). "In our patient, the mesenchymal tumor is localized to the C7-T1 spine and is likely the source of the excessive secretion of FGF23." (PMID 40922882, 2025). "The detection of FGF-23 expression in tumor tissues is of significant value for differentiating PMT from other mesenchymal tumors with overlapping histological features." (PMID 40406261, 2025). "TIO has been associated with increased production of the phosphaturic hormone Fibroblast Growth Factor 23 (FGF23) usually by mesenchymal tumors of soft tissue or bone (Phosphaturic Mesenchymal Tumors—PMTs)." (PMID 38806758, 2024). "This type of mesenchymal tumor typically produces FGF23, a hormone crucial for phosphate homeostasis, leading to musculoskeletal deficiencies." (PMID 39493128, 2024). "Next-generation sequencing (NGS) showed an appreciable rise in FGFR1 and FGF23, affirming the diagnosis of a phosphaturic mesenchymal tumor." (PMID 39185431, 2024). "In contrast, for phosphaturic mesenchymal tumours, a direct correlation between FGF23 expression and this paraneoplastic syndrome has been identified." (PMID 38397231, 2024). "TIO is caused by phosphaturic mesenchymal tumours (PMT), which secrete fibroblast growth factor 23 (FGF23)." (PMID 38542041, 2024). "First described by McCance and Prader, TIO has been associated with increased production of the phosphaturic hormone Fibroblast Growth Factor 23 (FGF23), usually by mesenchymal tumors of soft tissue or bone known as “Phosphaturic Mesenchymal Tumors” (PMTs)." (PMID 38806758, 2024). "Patients with TIO typically exhibit hypophosphataemia, hyperphosphaturia, and elevated FGF23 levels, prompting clinicians to incorporate bone imaging modalities to identify the mesenchymal tumour responsible for these laboratory abnormalities." (PMID 38542041, 2024). "This is due to an overproduction of fibroblast growth factor 23 (FGF23) from benign mesenchymal tumors, leading to disruptions in renal metabolism, lowered vitamin D3 concentration, and decreased phosphate reabsorption." (PMID 39185431, 2024). "TIO is an uncommon disorder connected with small, benign mesenchymal tumors that produce fibroblast growth factor 23 (FGF23)." (PMID 39314547, 2024). "TIO is caused by a phosphaturic mesenchymal tumor (PMT), mostly benign, that expresses and secretes fibroblast growth factor-23 (FGF23), or in rare cases, other phosphatonins, in increased amounts." (PMID 37980279, 2023). "Tumor-induced osteomalacia (TIO) is an uncommon paraneoplastic syndrome predominantly due to the overproduction of fibroblast growth factor 23 (FGF23) by mesenchymal tumors usually involving bone and soft tissues." (PMID 37436671, 2023). "In TIR and TIO, small mesenchymal tumors secrete FGF23 and/or other phosphatonins such as matrix extracellular phosphoglycoprotein (MEPE)." (PMID 33815294, 2021). "In conclusion, we here describe a patient with an FGF-23-secreting phosphaturic mesenchymal tumor with an unusual morphology." (PMID 31963334, 2020). "A fibroblast growth factor 23-producing phosphaturic mesenchymal tumor localized in the left quadriceps femoris muscle was identified 7 years after onset of symptoms." (PMID 27709474, 2016). "A repeat CT guided needle biopsy of L-4 showed a low grade spindle cell neoplasm with positive FGF-23 mRNA expression by RT-PCR, confirming the diagnosis of mixed phosphaturic mesenchymal tumor (PMT)." (PMID 23346426, 2012). "The pathophysiology of OOM involves the production of FGF23 by mesenchymal tumors." (PMID 41438661, 2026). "However, in a substantial subset of patients with acquired FGF23-related hypophosphatemic osteomalacia, phosphaturic mesenchymal tumors (PMTs) remain undetectable despite extensive imaging studies." (PMID 41691126, 2026). "Additionally, regular follow-up imaging is crucial to continue searching for mesenchymal tumors, as surgical resection offers a curative option by eliminating the source of FGF-23 overproduction." (PMID 40951211, 2025).